GCG (glucagon)
Diseases named in the same sentence as GCG in open-access papers (continued):
Sharing a sentence is not in itself a finding about the gene and the disease.
Hypoglycemia (continued). "Persistent suppression of α-cell response may result in defective glucose counterregulation, leading to insulin-induced hypoglycemia, as a consequence of lacking hepatic glucose production under glucagon-stimulated conditions." (PMID 23316165, 2012). "It was questioned whether somatostatin plays a role during hypoglycemia because somatostatin-secreting δ-cells are downstream of glucagon-secreting α-cells in the islet microcirculation of non-diabetic rats." (PMID 22969729, 2012). "A similar analysis was performed for HY TME in SGH that exhibit a loss of body mass during the late clinical phase of disease and these animals have a different profile that includes hypersecretion of glucagon, increased fasted ß-ketones, fasted hypoglycemia, and suppressed, non-fasted leptin." (PMID 22174765, 2011). "But, it does not decrease normal glucagon response to hypoglycemia (when needed)." (PMID 20582183, 2010). "Furthermore, antecedent hypoglycemia affected glycemic parameters, but not the glucagon response in SSTR2a-treated rats, as blood glucose nadirs were lower (P < .01) and blood glucose AUC less than 3.9 mmol/L higher (P < .0001) in challenges 3 and 4 than in the first 2 challenges." (PMID 41502124, 2026). "Mechanistically, GLP-1 enhances glucose-dependent insulin secretion, suppresses glucagon release, and delays gastric emptying, whereas GIP primarily augments insulin secretion under hyperglycemic conditions but may stimulate glucagon secretion during hypoglycemia." (PMID 41404505, 2025). "However, these responses can be blunted, and glucagon secretion during insulin-induced hypoglycemia is usually impaired, if not completely absent, thereby raising the question as to whether the α cell is an accessible target to reduce hypoglycemic risk." (PMID 37166980, 2023). "In people with T1DM, glucagon secretion may not increase sufficiently in response to hypoglycemia." (PMID 37630716, 2023). "Since it was effective for restoring glucagon release in animals, it has been postulated that ZT-01 may be able to restore the absent or diminished glucagon responses to hypoglycemia in individuals with T1D, although this effect has yet to be fully studied in humans." (PMID 36992764, 2022). "The absent glucagon responses to hypoglycemia in type 1 diabetes is a scenario specific to hypoglycemia, since other stimuli, including administration of amino acids, insulin withdrawal, lipopolysaccharide exposure, exercise and even meals lead to profound glucagon responses." (PMID 34405569, 2021). "Moreover, in contrast to GLP-1, GIP has a glucagonotropic action in humans, which, however, depends on the prevailing glucose concentrations: glucagon secretion is increased by GIP in the presence of euglycemia or hypoglycemia but not in the presence of hyperglycemia." (PMID 33419065, 2021). "However, new routes, such as intranasal glucagon, recently approved by FDA to treat hypoglycemia, might also prove effective, although to our knowledge there is insufficient information about its effectiveness in provoking the release of GH.Our study has several limitations." (PMID 32720093, 2021). "Taken together, these actions of R481 suggest that the compound does not alter glucagon secretion through a pancreatic α-cell-mediated mechanism and provides evidence that in vivo, R481 may raise glucagon levels during hypoglycemia by a centrally-mediated pathway." (PMID 34975743, 2021). "Additionally, there was an increase in glucagon secretion in response to the WPI preload during the OGTT in both groups on Days 1 and 7, an effect that could have occurred to combat falling glucose levels to prevent hypoglycemia." (PMID 34371959, 2021). "Importantly, induction of hypoglycemia by portal glucose infusion is ablated in RIP-GLUT1/GLUT2 mice, indicating a major role for GLUT2 as a glucose sensor in the hepatoportal vein area, indirectly controlling pancreatic glucagon secretion via the nervous system." (PMID 32591906, 2020).
Hypoglycemia (continued). "Over the following weeks in particular intravenous treatment (glucose, glucagon) and dietary treatment was subsequently reduced to allow discharge with the minimum of additional carbohydrates compared to dietary recommendations without a substantial worsening of hypoglycaemia rate or severity." (PMID 28576129, 2017). "In this regard, repeated hypoglycemia leads to a defect in hypoglycemia-induced activation of counter-regulatory mechanisms (namely, an attenuation of the normal epinephrine response to hypoglycemia, whilst insulin is not reduced and glucagon not increased by low glucose)." (PMID 26918849, 2016). "It should be cautioned that glucagon secretion in response to hypoglycemia does not improve with either allo- or auto-transplantation of islets into the liver, in human or animal studies, as described with pancreas transplant, and may be related to their location in the liver." (PMID 25013624, 2012). "Given that maternal hypoglycemia leads to fetal growth retardation, it is likely that the persistently lower blood glucose levels that is observed in Gcgr−/− mice is responsible for the growth failure of Gcgr−/− pups born to Gcgr−/− dams, rather than the absence of glucagon action." (PMID 22928026, 2012). "During insulin-induced hypoglycemia, GLP-2 did not compromise nor potentiate the counterregulatory glucagon response or responses of the counterregulatory hormones norepinephrine and growth hormone." (PMID 41541287, 2026). "We show that insulin-evoked hypoglycemia is severely aggravated in mice lacking the cation channel proteins TRPC1, TRPC4, TRPC5, and TRPC6, which cannot be explained by alterations in glucagon or glucocorticoid action." (PMID 39375537, 2024). "Clinically, glucose levels below 70 mg/dL initiate neuroendocrine responses to hypoglycemia in people without diabetes, whereas people with type 1 diabetes and hypoglycemia unawareness might have this response occur at a lower glucose threshold, partly due to the absent glucagon response." (PMID 37887414, 2023). "Induction of AMPK by AMP is mediated by LKB1 during hypoglycemia, but AMPK is not the sole target of LKB1 phosphorylation in glucagon regulation." (PMID 35002748, 2021). "Islet autonomic innervation may also be involved in the regulation of glucagon secretion, although it does not appear to be critical for glucagon secretion as humans with spinal cord transections and the denervated transplanted human pancreas secrete glucagon when subjected to hypoglycemia." (PMID 34405569, 2021). "Glucose and glucagon level during an MMT were significantly lower after lixisenatide, without affecting counter‐regulatory response during hypoglycaemia." (PMID 32704555, 2020). "Third, because glucagon level s were not measured, the mechanism by which SGLT2 inhibitors suppress the likely development of hypoglycemia was not sufficiently examined." (PMID 28785316, 2017). "Here, using a sensitive and specific glucagon assay, we show that exogenous GLP-2, compared to placebo, increases glucagon secretion only slightly during euglycemia, and not during hyperglycemia or insulin-induced hypoglycemia in healthy men." (PMID 41541287, 2026). "One promising approach involves the use of mini-dose glucagon (MDG), which may offer a safe and effective method to treat and prevent non-severe hypoglycemia in individuals with T1D." (PMID 41510436, 2025). "Taken together, while the effects of GLP-1RA therapy on glucagon regulation during a MMTT appear heterogeneous, all studies consistently show that treatment with GLP-1RA does not reduce glucagon levels during hypoglycemia when its counter-regulatory action is essential." (PMID 40760325, 2025). "Additionally, our study showed that the stimulatory effect of adrenaline on glucagon secretion in physiological levels does not prevail over the suppressive effect of insulin, which may be highly relevant when individuals with type 1 diabetes experience insulin-induced hypoglycaemia." (PMID 38427076, 2024).
Hypoglycemia (continued). "A negative correlation between glucagon and RAGE expression in the islets was found in 50% of type 1 diabetes donors, including three adolescents and a donor with a clinical history of hypoglycemia, alluding to a possible link between islet RAGE expression and the risk of a hypoglycemic event." (PMID 37558746, 2023). "Finally, in RH rats pre-treated with NAC (0.5% in drinking water for 9 days) hypoglycemia-induced VMH ROS production was prevented and glucagon and epinephrine production was not blunted in response to subsequent insulin-hypoglycemia." (PMID 23894333, 2013). "In support of this, it has been shown in dogs that acutely lowering liver glycogen content, such as occurs in response to fasting, decreases glucagon and HGP responses to hypoglycemia, although it has not yet been determined whether this effect translates to humans." (PMID 37166980, 2023). "The mice globally lacking GLUT2 exhibited elevated blood glucagon levels and a decreased glucagon secretion in response to fluctuations in systemic glucose, a phenotype which illustrates that GLUT2 is essential for the counterregulatory response to hypoglycemia." (PMID 34201099, 2021). "Moreover, when insulin and glucagon levels were combined in the IGR, lower IGR was observed in the group without hypoglycemia, suggesting a catabolic status with increased hepatic glucose output and further stressing hypothesis." (PMID 33424773, 2020).
Hyperglycemia (754 papers, 2006 to 2026). An increased concentration of glucose in the blood. "Although glucagon is also effective, it can cause electrolyte imbalances such as hyperkalemia and hyperglycemia." (PMID 41321955, 2026). "There is also a compensatory increase in glucagon secretion, which can cause an acute rebound hyperglycaemia if treatment is missed or stopped." (PMID 41174263, 2026). "The bolus dose calculations in current AID systems do not account for the consumption of other macronutrients, and as previously discussed, the glucagon response following protein consumption is unopposed in T1D which can cause delayed hyperglycemia." (PMID 41602572, 2026). "Basal hyperglycemia is caused by a lower insulin-to-glucagon ratio resulting in increased production of glucose by the liver." (PMID 39859258, 2025). "We find that male gonads make mice susceptible to isolation-induced hyperglycemia and increased levels of gluconeogenic glucagon." (PMID 41509225, 2025). "The biochemical signals between cells of different tissues such as the pancreas, liver, fat, and skeletal muscle by glucagon and insulin are likely candidates responsible for hyperglycemia and the loss of antagonism by the single-node inhibitors." (PMID 39456616, 2024). "In genetic mouse models of glucagon resistance, in which mTORC1 signalling is upregulated, mice exhibit chronic hyperglucagonaemia associated with hyperglycaemia, and reduced glucose excursion in response to a glucagon tolerance test." (PMID 38579751, 2024). "Hyperglycemia itself causes dilation of the afferent arteriole through the release of vasoactive mediators such as insulin-like growth factor 1, glucagon, VEGF and prostaglandins." (PMID 39011442, 2024). "Although effective at reducing psychoses, APs cause rapid hyperglycemia, insulin resistance, and dyslipidemia, an effect mediated in part by glucagon." (PMID 38188526, 2024). "The loss of β cells leads to abnormal behavior of α cells, causing glucagon hypersecretion that exacerbates hyperglycemia through stimulation of gluconeogenesis and glycogenolysis." (PMID 38258903, 2024). "Insufficient glucagon secretion during hypoglycemic episodes raises the risk of hypoglycemic shock, while excessive glucagon in a postprandial state can worsen hyperglycemia." (PMID 39594662, 2024). "Insulin insensitivity, insulin insufficiency or elevated glucagon are the main causes of hyperglycaemia." (PMID 39571901, 2024). "Stress‐induced increases in glucagon, cortisol, and catecholamine release promote glycogenolysis and gluconeogenesis, eventually causing hyperglycemia." (PMID 38769875, 2024). "This is a scenario that substantiates the notion that glucagon plays a significant role in the cause of hyperglycemia in diabetics as glucagon stores remain unaffected in diabetics." (PMID 38665134, 2024). "The risk of developing pasireotide-induced hyperglycemia is the highest in patients with high glucagon levels, HbA1c > 34.5 mmol/L (5.3%), and glucose peak > 9 mmol/L after pasireotide administration." (PMID 37139336, 2023). "These caused wrongful glucagon administration and hyperglycemia, which was followed by increased insulin supply when the augmentation was resolved." (PMID 36755913, 2023). "High levels of glucagon cause hyperglycaemia because they accelerate gluconeogenesis and glycogenolysis and inhibit glycolysis and glycogen synthesis." (PMID 37842314, 2023). "Scorpion venom causes hyperglycaemia via different mechanisms such as massive catecholamine release, glucagon release, and glucocorticoid release, affecting renin–angiotensin–aldosterone system, causing hyperinsulinemia and cytokines release, etc.." (PMID 37624261, 2023). "Increased counterregulatory hormones (cortisol, catecholamines, growth hormone, and glucagon) and proinflammatory cytokines interfere with carbohydrate metabolism, causing hyperglycemia in patients with acute medical or surgical conditions." (PMID 38132485, 2023).
Hyperglycemia (continued). "The presence of both GLP1 and GIP components within the same molecule is reported to more effectively minimize the risk of glucagon-mediated hyperglycaemia, and thereby permit more aggressive dosing to achieve additional weight reduction." (PMID 34815532, 2022). "* Excessive amounts of glucagon are frequently released in individuals with T1D after meals, and these higher levels can cause hyperglycemia after eating and insulin resistance." (PMID 36992764, 2022). "Based on its pathophysiology, hyperglycemia can be caused by insulin resistance caused by excess fatty acids and proinflammatory cytokines, causing an inappropriate increase in glucagon." (PMID 36612560, 2022). "Postprandial hyperglycemia arises from delayed and deficient insulin secretion as well as impaired suppression (or a paradoxical rise) of glucagon concentrations." (PMID 35822422, 2022). "This demonstrates that hyperglycemia is driving the loss of beta cells while increasing both the alpha cell numbers and function, illustrated by the significantly increased glucagon levels." (PMID 35203411, 2022). "In both type-1 diabetes (T1D) and type-2 diabetes (T2D), hyperglycemia results from a combination of complete/partial loss of insulin secretion and over-secretion of glucagon." (PMID 34787082, 2021). "High glucagon levels after oral food intake are associated with postprandial hyperglycemia in patients with T1DM." (PMID 34571911, 2021). "In rats, mechanisms associated to stimulation or inhibition of glucagon release includes hyperglycemia and hypertriglyceridemia, respectively." (PMID 34115756, 2021). "GIP receptor agonism and GLP-1 receptor agonism limit the hyperglycemia caused by glucagon and improves insulin sensitivity." (PMID 34577569, 2021). "GLP-1R regulation is dependent on glucagon secretion, in a glucose-dependent manner; which means it reduces the risk of hyperglycemia or hypoglycemia." (PMID 34207217, 2021). "The activation of the SNS also causes the inhibition of glucose-stimulated insulin secretion and the increase of glucagon secretion via the α-receptor, caused hyperglycemia." (PMID 34805193, 2021). "In T2D, loss of the suppressive effects of glucagon and insulin is associated with hyperglucagonaemia and this is thought to contribute to hyperglycaemia." (PMID 34566894, 2021). "In this syndrome, an increase in glucagon secretion and a decrease in insulin secretion occur, which cause hyperglycemia and the development of dehydration." (PMID 34912875, 2021). "The systemic administration of 2-DG produces hyperglycemia and initiates the sympathoadrenal counterregulatory response causing both epinephrine and glucagon to be released peripherally." (PMID 31013147, 2019). "We have explored the mechanism underlying hyperglycemia-induced dysregulation of glucagon secretion and our data highlight a critical role for Na+-glucose co-transport (SGLT)-mediated Na+ uptake and intracellular acidification." (PMID 30415925, 2019). "Double allele knockout of the mouse SLC2A2 gene resulted in severe hyperglycemia, low insulin, and high glucagon in the blood." (PMID 31540540, 2019). "If the dysregulation of glucagon secretion in diabetic Fh1βKO is caused by hyperglycemia, then it should be possible to reverse the secretion defect simply by culturing the islets at normal glucose." (PMID 30415925, 2019). "Is glucagon essential for the hyperglycemia in insulin deficiency, as suggested by experimental glucagon antagonism?" (PMID 28323959, 2017). "GLP-1 receptor agonists stimulate glucose-medicated insulin secretion, suppress glucagon secretion, delay gastric emptying, and decrease appetite, thus explaining the considerable effect of these drugs on postprandial hyperglycemia and weight loss." (PMID 28115994, 2017).